SMPD1 (sphingomyelin phosphodiesterase 1)
Description:
Converts sphingomyelin to ceramide. Exists as two enzymatic forms that arise from alternative trafficking of a single protein precursor, one that is targeted to the endolysosomal compartment, whereas the other is released extracellularly. However, in response to various forms of stress, lysosomal exocytosis may represent a major source of the secretory form. In the lysosomes, converts sphingomyelin to ceramide. Plays an important role in the export of cholesterol from the intraendolysosomal membranes. Also has phospholipase C activities toward 1,2-diacylglycerolphosphocholine and 1,2-diacylglycerolphosphoglycerol. Modulates stress-induced apoptosis through the production of ceramide. When secreted, modulates cell signaling with its ability to reorganize the plasma membrane by converting sphingomyelin to ceramide. Secreted form is increased in response to stress and inflammatory mediators such as IL1B, IFNG or TNF as well as upon infection with bacteria and viruses. Produces the release of ceramide in the outer leaflet of the plasma membrane playing a central role in host defense. Ceramide reorganizes these rafts into larger signaling platforms that are required to internalize P.aeruginosa, induce apoptosis and regulate the cytokine response in infected cells. In wounded cells, the lysosomal form is released extracellularly in the presence of Ca(2+) and promotes endocytosis and plasma membrane repair. [Sphingomyelin phosphodiesterase, processed form]: This form is generated following cleavage by CASP7 in the extracellular milieu in response to bacterial infection. It shows increased ability to convert sphingomyelin to ceramide and promotes plasma membrane repair (By similarity). Plasma membrane repair by ceramide counteracts the action of gasdermin-D (GSDMD) perforin (PRF1) pores that are formed in response to bacterial infection (By similarity). (Microbial infection) Secretion is activated by bacteria such as P.aeruginosa, N.gonorrhoeae and others, this activation results in the release of ceramide in the outer leaflet of the plasma membrane which facilitates the infection. (Microbial infection) Secretion is activated by human coronaviruses SARS-CoV and SARS-CoV-2 as well as Zaire ebolavirus, this activation results in the release of ceramide in the outer leaflet of the plasma membrane which facilitates the infection. [Isoform 2]: Lacks residues that bind the cofactor Zn(2+) and has no enzyme activity. [Isoform 3]: Lacks residues that bind the cofactor Zn(2+) and has no enzyme activity.
Synonyms: aSMase; ASM; NPD
Tractability: Small molecule: a structure with a bound ligand is known; a high-quality ligand is known. Antibody: UniProt places it where antibodies can reach, with high confidence; its Gene Ontology location is reachable by antibodies, with high confidence; UniProt predicts a signal peptide or a membrane-spanning region. PROTAC: its protein half-life has been measured; a small molecule that binds it is known.
Target class: Enzyme; Phosphodiesterase
Gene: Protein-coding gene on chromosome 11 (6,390,414 to 6,394,998, forward strand). Ensembl gene ENSG00000166311.
Subcellular location: Lysosome; Lipid droplet; Secreted; Secreted, extracellular space (Sphingomyelin phosphodiesterase, processed form)
Pathways (Reactome):
Hemostasis: Regulation of clotting cascade
Metabolism: Glycosphingolipid catabolism
Gene Ontology:
Molecular function: acid sphingomyelin phosphodiesterase activity; phosphatidylcholine phospholipase C activity; protein binding; sphingomyelin phosphodiesterase activity; zinc ion binding; hydrolase activity
Biological process: cellular response to calcium ion; cellular response to UV; ceramide biosynthetic process; negative regulation of MAPK cascade; plasma membrane repair; positive regulation of apoptotic process; positive regulation of endocytosis; positive regulation of viral entry into host cell; response to interleukin-1; response to ionizing radiation; response to tumor necrosis factor; response to type I interferon; response to virus; sphingomyelin catabolic process; symbiont entry into host cell; termination of signal transduction; wound healing; blood coagulation; glycosphingolipid catabolic process; nervous system development; signal transduction; sphingomyelin metabolic process; response to cocaine; response to xenobiotic stimulus
Cellular component: endolysosome; endosome; extracellular exosome; extracellular region; lysosome; plasma membrane; endolysosome lumen; lysosomal lumen; lamellar body; lipid droplet
Genetic constraint (gnomAD): Loss-of-function variants: 47 observed, 56.69 expected, observed/expected ratio (o/e) 0.83, 90% interval 0.65 to 1.06. The upper end of that interval is the gene's LOEUF score, 1.06, which puts it in group 4 of 6, group 1 being the genes least tolerant of losing a copy. Missense variants: 807 observed, 845.58 expected, observed/expected ratio (o/e) 0.95, 90% interval 0.9 to 1.01. Synonymous variants: 335 observed, 349.43 expected, observed/expected ratio (o/e) 0.96, 90% interval 0.88 to 1.05.
Gene-disease validity (ClinGen):
ClinGen rates the evidence that SMPD1 causes each of these diseases.
acid sphingomyelinase deficiency (autosomal recessive): Definitive. An autosomal recessive lysosomal disease caused by biallelic loss of function variants in the SMPD1 gene.
Homologues: Orthologues: macaque SMPD1 (97% identical), rabbit SMPD1 (88% identical), dog SMPD1 (85% identical), pig SMPD1 (83% identical), rat Smpd1 (82% identical), mouse Smpd1 (82% identical), guinea pig SMPD1 (81% identical), chimpanzee SMPD1 (78% identical), tropical clawed frog smpd1 (56% identical), zebrafish smpd1 (52% identical), Caenorhabditis elegans asm-2 (34% identical), Caenorhabditis elegans asm-3 (32% identical), and 3 more. Paralogues in human: SMPDL3A (21% identical), SMPDL3B (20% identical).
Diseases named in the same sentence as SMPD1 in open-access papers:
SMPD1 is named in the same sentence as 213 diseases in open-access papers, as found by Europe PMC text mining. Sharing a sentence is not in itself a finding about the gene and the disease. The quoted sentences say what the papers report.
Niemann-Pick disease (68 papers, 2008 to 2026). A group of inherited, severe metabolic disorders in which sphingomyelin accumulates in lysosomes in cells. "The two main forms—acid sphingomyelinase-deficient Niemann–Pick disease (ASM-deficient NPD) types A and B and intermediate forms—are both inherited in an autosomal recessive manner and caused by mutations in the SMPD1 gene." (PMID 41614773, 2025). "HDL cholesterol is lower in patients with congenital disorders of lipid metabolism, such as Niemann–Pick disease, which is caused by the deletion of sphingomyelin phosphodiesterase 1 (SMPD1), another member of the SMPD family." (PMID 39917667, 2024). "Some genetic variants in the Sphingomyelin phosphodiesterase 1 (SMPD1) gene for example, known for Niemann Pick disease (acid sphingomyelinase deficiency), have also been implicated in increasing the risk of PD." (PMID 38153678, 2024). "Niemann–Pick disease has also been shown to be related to variants in SMPD1, and type A Niemann–Pick disease manifests with central nervous system abnormalities." (PMID 37679557, 2024). "Homozygous ASM knockout (ASM−/−) mice manifest a progressive buildup of sphingomyelin, leading to the development of symptoms similar to those observed in human Niemann–Pick disease caused by mutations in the corresponding gene SMPD1." (PMID 39201372, 2024). "It has been reported that disease-causing mutations in the SMPD1 lead to abnormal ASMase activity, resulting in lysosomal storage disorders, such as Niemann-Pick disease." (PMID 39698091, 2024). "Niemann-Pick disease is an autosomal recessive disorder, caused by mutations in the SMPD1 gene for type A and B Niemann-Pick disease." (PMID 39416542, 2024). "Niemann–Pick disease is an autosomal recessive disorder caused by mutations in SMPD1 causing a deficiency in acid sphingomyelinase and, thus, an accumulation of sphingomyelin." (PMID 38891023, 2024). "ASM deficiency is caused by autosomal recessive mutations in SMPD1, and this disease is known as Niemann–Pick diseases in human." (PMID 37710183, 2023). "In a similar fashion to GBA1 mutations, homozygous mutations in SMPD1 (encoding acid sphingomyelinase or ASM) also cause an LSD, in this case, Niemann–Pick disease, whereas heterozygous SMPD1 variants are associated with increased risk of sporadic PD." (PMID 36951087, 2023). "All patients with types A and B Niemann-Pick disease have mutations in the gene encoding ASM (SMPD1) and thus the disease is more accurately referred to as ASM deficiency (ASMD)." (PMID 37759536, 2023). "Mutations in SMPD1 are associated with sphingomyelin lipidosis, also called sphingomyelinase deficiency or Niemann-Pick disease (NPD) type A/B, a rare lipid storage disorder with autosomal recessive inheritance." (PMID 35943990, 2022). "Mutation in SMPD1 is associated with sphingomyelin lipidosis, sphingomyelinase deficiency or Niemann-Pick disease (NPD) type A/B." (PMID 35943990, 2022). "Niemann–Pick disease (NPD) is a rare disorder that is characterized by the deficiency of aSMase (types A and B; mutation in SMPD1 gene) or the inability to traffic cholesterol and other lipids throughout the cell (type C; mutations in NPC1 or NPC2)." (PMID 34071409, 2021). "Among them, mutations in genes encoding the lysosomal proteins glucocerebrosidase (GBA1 gene) and sphingomyelinase (SMPD1 gene), faulty in Gaucher’s and Niemann-Pick diseases, respectively, have been connected to a higher predisposition to develop PD65." (PMID 33414430, 2021). "We have identified five different disease causing mutations of SMPD1 gene in Niemann-Pick disease unrelated patients from consanguineous families." (PMID 32292456, 2020). "Excess SM that occurs in SMPD1 (sphingomyelin phosphodiesterase 1, acid lysosomal)-deficiency (Niemann-Pick diseases) prevents autophagosome closure by defective regulation of ATG9 (autophagy related 9) cycling during autophagosome maturation." (PMID 31517566, 2020).
Niemann-Pick disease (continued). "Niemann-Pick disease (types A and B) is an autosomal recessive lysosomal storage disorder caused by biallelic mutations in the SMPD1 gene resulting in a severe human disease state characterized by deficient ASM activity." (PMID 33553211, 2020). "An inherited deficiency of the sphingomyelin-cleaving hydrolase, ASM (encode by SMPD1), causes the phospholipid accumulation in Niemann–Pick disease patients." (PMID 32272755, 2020). "Bovine homologs for the genes that cause Niemann-Pick disease in humans (SMPD1, NPC1 and NPC2), are located on BTA15, BTA24 and BTA10 respectively." (PMID 32970694, 2020). "Mutations in the Smpd1 gene cause types A and B Niemann-Pick disease, which is a family of metabolic disorders." (PMID 28575045, 2017). "Types A and B Niemann-Pick disease are autosomal-recessive sphingolipidosis caused by mutations in the sphingomyelin phosphodiesterase 1 gene (SMPD1, MIM# 607608, GenBank# M81780.1) resulting in lysosomal acid sphingomyelinase (ASM, E.C. 3.1.4.12) malfunction." (PMID 25811928, 2015). "Acid sphingomyelinase (ASMase) deficiency in Niemann–Pick disease due to mutations in the SMPD1 gene leads accumulation of sphingomyelin in the affected tissues including the kidney." (PMID 25126087, 2014). "Clinical observations and molecular analysis of the SMPD1 gene in Chinese patients with acid sphingomyelinase deficiency Niemann-Pick disease (NPD) are scarce." (PMID 23356216, 2013). "Acid sphingomyelinase (ASM) deficient Niemann-Pick disease (NPD) is caused by SMPD1 gene mutations and subsequent acid sphingomyelinase deficiency." (PMID 23356216, 2013). "Since missense mutations in SMPD1 are pathogenic and can cause Niemann-Pick disease, it is hypothesized that a morphological link exists between Niemann-Pick cells and sea-blue histiocytes." (PMID 41991317, 2026). "Genetic deficiencies in enzymes involved in sphingolipid metabolism, such as ASAH1 and SMPD1, are associated with lysosomal sphingolipid storage disorders such as Farber disease and Niemann-Pick disease, respectively, emphasizing the importance of maintaining proper sphingolipid balance." (PMID 41167398, 2025). "Likewise, mutations in the NPC1 (NPC intracellular cholesterol transporter 1) and SMPD1 (sphingomyelin phosphodiesterase 1) genes, which cause Niemann-Pick disease, have been shown to be risk genes for IPD." (PMID 36525454, 2022). "Clinical studies have related SMPD1 variants impacting on enzyme activity to the Niemann-Pick disease (NPD), an autosomal recessive disorder characterized by a wide variety of pathological symptoms, ranging from jaundice and enlarged abdomen to neurological development delays and death." (PMID 33925997, 2021). "Niemann-Pick diseases thus oppose two clearly distinct groups: acid sphingomyelinase deficiencies (due to SMPD1 mutations, including types A, B and intermediate forms,) and Niemann-Pick type C, with alterations in trafficking of endocytosed cholesterol (due to NPC1 or NPC2 mutations)." (PMID 20525256, 2010). "Notably, mice that are deficient in enzymes that we found to be downregulated in the Mwk cerebellum also display cerebellar dysfunction including Scp2 knockout mice, Smpd1-deficient mice, a model of Niemann-Pick disease, and Gm2a knockout mice, a model of GM2-gangliosidosis." (PMID 25908616, 2015). "Niemann-Pick disease (NPD) A/B is a lysosomal storage disease (LSD), caused by an autosomal recessive disorder that causes variation in sphingomyelin phosphodiesterase-1 (SMPD1)." (PMID 36779112, 2023). "Background and Aims: Niemann–Pick disease (NPD) types A (NPA) and B (NPB) are caused by deficiency of the acid sphingomyelinase enzyme, which is encoded by the SMPD1 gene, resulting in progressive pathogenic accumulation of lipids in tissues." (PMID 35011993, 2022).
Niemann-Pick disease (continued). "The analysis in this section shows that the SMPD1-ZooM predictor can be used not only in the framework of Niemann-Pick disease, but also as a tool to gain insights into the role of SMPD1 in other disorders such as PD." (PMID 33925997, 2021). "Acid sphingomyelinase deficiency (ASMD) (historically Niemann–Pick disease [NPD] types A [OMIM257200], B [OMIM607616], A/B) results from pathogenic sequence variants in the SMPD1 (EC3.1.4.12) gene encoding the lysosomal enzyme acid sphingomyelinase (ASM)." (PMID 33875845, 2021). "Mutations in the aSMase (SMPD1) gene results in disfunction of cholesterol and lipids metabolism, leading to Niemann-Pick’s disease." (PMID 34202192, 2021). "We sequenced the SMPD1 gene including its all coding and flanking regions in seven unrelated sporadic patients suffering from Niemann-Pick disease through targeted exome sequencing." (PMID 32292456, 2020). "The complete knock-out of SMPD1 gene results in Niemann-Pick disease which is characterized by rapid central nervous degeneration alongside an impairment of liver function." (PMID 28955042, 2017). "The occurrence of lipid-laden macrophages resembling foam cells was described in the bone marrow, liver, and kidney in patients with Niemann–Pick disease and in SMPD1 knockout mice." (PMID 25126087, 2014). "Niemann-Pick disease (< 1-9/100000, ORPHA645) is a lysosomal lipid storage disease caused by mutations in the sphingomyelin phosphodiesterase 1 (SMPD1) gene, which results in the deficient activity of lysosomal acid." (PMID 22284844, 2012). "Niemann-Pick Disease (NPD) is a rare autosomal recessive lysosomal storage disorder (LSD) caused by the deficiency of acid sphingomyelinase (ASMD), which is encoded by the Smpd1 gene." (PMID 40166006, 2025). "Acid sphingomyelinase deficiency (ASMD), also known as Niemann–Pick disease (NPD) types A or B, is an extremely rare genetic disorder characterised by mutations in the SMPD1 (sphingomyelin phosphodiesterase 1) gene, leading to a deficiency of the enzyme acid sphingomyelinase (ASM)." (PMID 33639994, 2021). "Sphingomyelin levels, along with those of cholesterol, are increased in the kidney of Niemann-Pick disease, a genetic disorder due to mutations in NPC1/NPC2 (encoding intracellular cholesterol transporters) and SMPD1 (encoding an acid sphingomyelinase) genes, the latter associated with proteinuria." (PMID 30939806, 2019). "Of note, a mutation in Sphingomyelin phosphodiesterase 1 (also known as acid sphingomyelinase, ASM) causes Niemann-pick disease, characterized by the buildup of toxic amount of sphingomyelin and leading to multi-organ dysfunction (including profound brain damage)." (PMID 29075199, 2017). "Sphingomyelin phosphodiesterase 1 (SMPD1) converts sphingomyelins (SMs) to ceramides and is involved in the regulation of immune cell functions and Niemann–Pick disease, a lysosomal storage disorder characterized by hepatosplenomegaly, jaundice, and cytopenia." (PMID 36292100, 2022). "Recessive mutations in the sphingomyelin phosphodiesterase 1 (SMPD1) gene are responsible for neuropathic (Type A) and non-neuropathic (Type B) Niemann-Pick disease (NPD), while heterozygous mutations are associated with an increased risk of developing PD." (PMID 32375870, 2020).